CD44 (CD44 molecule (IN blood group))
Diseases named in the same sentence as CD44 in open-access papers (continued):
Sharing a sentence is not in itself a finding about the gene and the disease.
breast carcinoma (continued). "The role of CD44 has been extensively studied in various tumors, such as intestinal cancer, breast cancer, and ovarian cancer, and is closely related to chemotherapeutic drug sensitivity and tumor cell adhesion and migration, but there is still a large gap in PAAD." (PMID 36359832, 2022). "Additionally, the migration and invasion abilities were decreased in CD44 knocked down breast cancer cells and increased in CD44-overexpressed cells." (PMID 36289750, 2022). "Ablation of catulin in the xenograft model revealed deregulation of genes involved in cellular movement, and adhesive properties with striking decrease in CD44 which may impact stemness potential, and plasticity of breast cancer cells." (PMID 35879327, 2022). "The study implies that Nav1.5 (VGSC) may regulate invasion in breast cancer via the CD44-src-cortactin signalling pathway." (PMID 35204811, 2022). "We also observed decrease in membrane localized CD44 protein, which may impact stemness potential and plasticity of breast cancer cells." (PMID 35879327, 2022). "This process is mediated by the breast cancer cell membrane-derived soluble CD44." (PMID 35464064, 2022). "HA binding to CD44 has been proven to promote JNK activation in breast cancer cells." (PMID 35215410, 2022). "CD44 can also modulate breast cancer metabolism under hypoxic conditions and promote EMT." (PMID 36289750, 2022). "Besides, many reports showed that estrogen E2, CD44, etc., mediated Ezrin to promote the malignant potential of breast cancer." (PMID 35311087, 2022). "CD44 has been known to increase the efficiency of distant metastasis in breast cancer." (PMID 35204811, 2022). "Additionally, the depletion of CD44 has been demonstrated to effectively prevent circulating tumor cell aggregation, which downregulates the tumorigenesis and metastasis of breast cancer." (PMID 35682836, 2022). "IL-6 can generate CD44+ CSCs via the induction of EMT in breast cancer cell T47D." (PMID 35464064, 2022). "proved that CD44 standard splice isoform can activate the PDGFRβ/Stat3 cascade and induce the cancer stem cell traits, which indicates that CD44 could be a potential target in inhibiting the progress of breast cancer." (PMID 36713450, 2022). "Inversely, HMGB3 silence decreased CD44+/CD24− subpopulation with stemness in breast cancer cells." (PMID 35416122, 2022). "CD44+CD24−/low is a well-known surface marker of breast cancer stem cell subpopulations." (PMID 36498950, 2022). "Furthermore, we found that CD44 mediated FOXA2 localization in breast cancer cells through the AKT pathway." (PMID 36289750, 2022). "Interestingly, four of those proteins (CD24, CD29, CD44 and CD146) have previously been associated with breast cancer." (PMID 35012489, 2022). "The observed moesin-mediated inhibition of CD44 signaling may contribute to removing breast cancer stem cells." (PMID 34976221, 2022). "Much previous evidence supports the role of HER2 in RT resistance, and HER2+/CD44+/CD24−/low cells, Fak activation in vitro and in vivo, and STAT3-survivin signaling may be associated with RT resistance in HER2+ breast cancer patients." (PMID 36686782, 2022). "Serglycin is constitutively secreted by breast cancer cells acting in an autocrine manner via binding to cell surface receptors such as CD44, a key mesenchymal and breast cancer stem cell marker gene, and integrins, possibly through its chondroitin sulfate (CS) chains." (PMID 35494005, 2022). "Reported biosensors for CD44 breast cancer biomarker detection." (PMID 36354475, 2022). "In basal breast cancer, expression of Slug enriches CD44+/CD24- stem-like populations." (PMID 36362141, 2022). "Previous studies reported that CD44 promotes the distant metastasis of breast cancer cells in vivo." (PMID 36289750, 2022). "Furthermore, another study has demonstrated the role of CD44 in promoting breast cancer invasion and tumor metastasis to liver in vivo." (PMID 36289750, 2022).
breast carcinoma (continued). "In addition, BXL0124, a Gemini vitamin D analog, was evaluated in basal-like breast cancer cells, resulting in decreased CD44+/CD24−/low population by inhibiting Notch1 signaling." (PMID 35743249, 2022). "In addition, CD44+ breast cancer cells, which are referred to as breast cancer CSCs, are frequently accompanied by activated TGF‐β signaling." (PMID 36226253, 2022). "Researchers remind that the importance of novel drug development in breast cancer and pipelines could be based on inhibitors of PTX-3/CD44 interaction or PTX-3 use in association with mesenchymal markers as the target." (PMID 36499628, 2022). "A previous study showed that soluble CD44 raised the level of IL-1β in breast cancer, and IL-1β could also be activated by soluble CD44 secretion." (PMID 35626430, 2022). "The result indicates that MSN's interaction with CD44 may contribute to repressing breast cancer stem cells." (PMID 34976221, 2022). "Indeed, previous studies have documented the potential involvement of calcium signaling in CD44+ breast cancer cells." (PMID 34743414, 2022). "CD44 is a putative marker of breast cancer stem cells (CSCs), and changes of its expression are implied in the transit between non-stem cancer cells (non-CSCs) and CSCs or shift between epithelial-CSCs and mesenchymal-CSCs, conferring to the high flexibility of cancer cells." (PMID 35680853, 2022). "CD44+CD24−/lo cell populations of multiple breast cancer cell lines demonstrated enhanced migration/invasion ability and a high correlation to asymmetric segregation of template DNA strands, which is one of the proposed mechanisms to achieve self-renewal of cancer stemness." (PMID 35883497, 2022). "The expression of key markers associated with proliferation (MKI67, PCNA, CCNB1, MYBL2, BUB1, CCND1), apoptosis (BCL2, CASP7, CASP8, CASP9, CASP3, BAX, APAF1), differentiation (CDH1, CD24, EPCAM, ESR1, NGFR, RUNX1), and breast cancer stemness (CD44, ITGA6, DNER, ALDH1A3, ABCG2, PROCR) was assessed." (PMID 35183258, 2022). "Hence, the developed GQDs-based electrochemical platform would pave the way to detect CD44 and other breast cancer biomarkers in real-life conditions." (PMID 36354475, 2022). "Moreover, several known surface markers of colorectal, glioblastoma, or breast cancer, including CD44, CD133, and CD147, have also been identified in OSCC CSCs." (PMID 36498950, 2022). "Indeed, Slug expression was found to correlate with CD44 levels in breast cancer cells at the single-cell level." (PMID 36291790, 2022). "Additionally, localization of CD44 within lipid rafts decreases during migration of highly invasive MDA-MB-231 breast cancer cells." (PMID 36439249, 2022). "Therefore, neutralization of CD44 by antibody decreased IL1β production in macrophages and attenuated the growth of primary breast cancer." (PMID 35464064, 2022). "In the research, the nano-carriers had good biosafety, and the CD44-mediated endocytosis of the nanohydrogels in human breast cancer cells MCF-7 showed significant internalization of up to 24 h incubation and exhibited higher cytotoxicity than free quercetin against human breast cancer cells MCF-7." (PMID 36091467, 2022). "In addition, ablation of α-catulin in the in vivo model resulted in decreased tumor size and decreased stemness potential of cancer cells with lowered expression of CD44, which is known to be enriched in breast cancer (BC) stem cells." (PMID 36233261, 2022). "Accordingly, it is reasonable to hypothesize that the frequency of CD44-/CD24- cells in human tumor specimens may be useful in the prediction of delayed breast cancer metastasis." (PMID 34318746, 2021). "However, detection of a direct interaction by co-immunoprecipitation of selectins with CD44 expressed by breast cancer cells has only been reported for E-selectin." (PMID 34829810, 2021).
breast carcinoma (continued). "Besides, Xu indicated that basal-like subtype possessed higher CD44 expression with more tendency of epithelial - mesenchymal transition, compared with luminal subtype of breast cancer." (PMID 34801088, 2021). "Furthermore, CD44+CD24−/low breast cancer CSCs isolated from both primary tumours and lung metastatic foci can generate orthotopic primary tumours and subsequent lung metastases." (PMID 34247196, 2021). "HART nanoassembly could achieve CD44-mediated intracellular uptake in MCF7 breast cancer cells and redox-responsive drug-gene release." (PMID 33925129, 2021). "Originally identified as self-renewing cells in leukemia with a CD34+CD38- phenotype, they have since been identified in several solid and hematologic malignancies, including breast cancer, as both hyperproliferative and slow-cycling cells with a consensus CD44+CD24-/ALDH1+ phenotype." (PMID 35582030, 2021). "Our study identifies MARCH8 as a new tumor suppressor in inhibiting breast cancer metastasis and enhancing cancer cell death, partially via the lysosomal degradation of the breast cancer stem-cell marker CD44, as well as via the proteosome-dependent degradation of STAT3." (PMID 34067416, 2021). "Moreover, compared with normal tissues adjacent to cancer, the breast cancer tissues had significantly up-regulated protein expression levels of CD44, N-cadherin, and β-catenin, but significantly down-regulated protein expression levels of E-cadherin and CD24." (PMID 34932597, 2021). "In addition, it has been shown that CD44+/CD24− subpopulation of breast cancer cells enhance the lung metastasis capacity due to their stem cell-like, progenitor and highly invasive characteristics." (PMID 34208799, 2021). "Further studies were carried out to demonstrate that circHIF1A from hypoxic CAFs exosomes regulated cancer cell stemness by sponging miR-580-5p which targeting CD44 expression in breast cancer, however, in normoxia, low levels of circHIF1A in CAFs exosomes maintains the low stem cell population." (PMID 34120145, 2021). "In this regard, the frequency of CD44-/CD24- cells in tumor tissues could be a valuable predictor of standard therapeutic response in breast cancer patients." (PMID 34318746, 2021). "Different subtypes and stages of breast cancer have their unique expression of stem cell markers such as CD44, CD24 and aldehyde dehydrogenase (ALDH) and the search for drugs which reduce cancer stemness is an essential investigation in drug discovery and development programs." (PMID 34208799, 2021). "Markedly lower levels of 1 accumulation were observed in cells with low tumorigenicity (MCF-7 breast cancer cells) and low CD44 expression or which are dysplastic and are unable to form tumours (DOK oral keratinocytes) despite the latter expressing reasonable levels of CD44 receptor." (PMID 34234213, 2021). "Mammospheres or breast cancer cells in hypoxia have higher expression of the KLF4, NANOG, OCT4, and SOX2 genes and CD44 and CD24, which encode pluripotency factors that are required for the maintenance of cancer stem cells, embryonic stem cells, and induced pluripotent stem cells." (PMID 34830821, 2021). "It is well established that CD44+CD24−/low cells were recognized as breast cancer stem cells." (PMID 33946480, 2021). "As the CD44+CD24− subpopulation is considered to exhibited cancer stem-like traits in breast cancer, we further investigated whether ALG3 affects the percentage of CD44+CD24−breast cancer cells." (PMID 33931075, 2021). "Mammospheres became less in the cells treated with CAFs exosomes with downregulation of circHIF1A and introduction of CD44 into the breast cancer cells could rescue the reduced sphere numbers." (PMID 34120145, 2021).
breast carcinoma (continued). "Breast cancer stem cells (BCSCs) can be identified by their CSC surface markers CD44+/CD24−/low." (PMID 34217266, 2021). "Breast cancer stem cells (BCSCs) own unique surface markers, such as CD44+CD24−/low10,11." (PMID 33934099, 2021). "In a breast cancer study, CTC subsets were selected for EpCAM negativity, positivity for stem cell markers (CD44+/CD24−) and combinatorial expression of uPAR/intβ1 because downregulation of these two markers has been directly implicated in breast cancer dormancy." (PMID 34026650, 2021). "CD44 is a stem marker of breast cancer and is very difficult to target." (PMID 34696797, 2021). "A recent study demonstrated that YB-1 regulated CD44 in primary breast cancer cells." (PMID 33451103, 2021). "Thus, the over-expression of ETV7 seems to drive a strong polarization of the analyzed breast cancer cells toward a more cancer stem-like cell phenotype represented by the CD44+/CD24− population." (PMID 34315857, 2021). "Because breast CSCs are crucial for the metastasis of breast cancer, whether CD44-/CD24- cells could convert into CSCs was tested in vitro and in vivo." (PMID 34318746, 2021). "In addition, CD44 is regarded as a stemness marker of breast cancer stem cells (BCSCs) (CD44+/CD24−/low) in TNBCs." (PMID 33801148, 2021). "Moreover, AURKA expression was also necessary to induce the expression of CD44 breast cancer stem-like cells marker." (PMID 33674749, 2021). "First, a retrospective analysis of CD44-/CD24- breast cancer cells in tissue specimens from patients enrolled from three academic medical centers was performed to investigate the potential associations between the frequency of CD44-/CD24- cells and postoperative tumor metastasis." (PMID 34318746, 2021). "In this study, HA was used as a ligand to target CD44 cells of breast cancer." (PMID 35431911, 2021). "A CD44 + / ALDH2 + /ALDH6A1 + cluster was defined as breast cancer stem cells (BCSCs)." (PMID 34611125, 2021). "For example, the HA receptor CD44 is misexpressed in Sdc-1-depleted breast cancer cells, and MDA-MB-231 breast cancer cells depleted of beta4GalT-7, a biosynthetic enzyme generating the HS GAG attachment site, respond with a reduced expression of Sdc-1 and an upregulation of HA biosynthesis." (PMID 34070901, 2021). "By further investigation, it was demonstrated that circHIF1A in hypoxic CAFs exosomes could regulate breast cancer cell stemness via miR-580-5p/CD44." (PMID 34120145, 2021). "Also, restoring and activating the PRL pathway was found to supress breast cancer stem-like cell (BCSC) subpopulations CD44+/CD24− and ALDH+ and reduced breast tumorigenesis in vitro and in vivo." (PMID 33446633, 2021). "The primary human and xenograft breast cancer CD44-/CD24- cells were purified from human fresh TNBC tissue cells or MDA-MB-231 xenograft tissue cells by flow cytometry sorting and cultured in L15 medium for 7 and 21 (specifically for cells from xenograft tissue cells) days, respectively." (PMID 34318746, 2021). "In addition, tumor sphere formation and expression of breast stem cell marker genes such as CD44/CD2 were greatly inhibited by CSNK1G2 knockdown in ER+ breast cancer cells." (PMID 33861751, 2021). "Furthermore, the co-expression analysis showed that LDHA was negatively correlated with the expression of ALDH1A1 but positively correlated with the expression of CD44 in human breast cancer samples based on the TCGA data set." (PMID 34178639, 2021). "have confirmed that CD44 expression was upregulated in breast cancer with bone or lung metastasis." (PMID 35004281, 2021). "In many cancers such as colon and breast cancer, CD44 acts as a significant marker on CSCs, however in many situations the specific isoforms are still unknown." (PMID 35431911, 2021).
breast carcinoma (continued). "After stratification of the training group of patients, based on their distant metastasis, the frequency of CD44-/CD24- cells in breast cancer tissues of patients with postoperative distant metastasis was significantly higher than those without distant metastasis (p<0.0001)." (PMID 34318746, 2021). "The CD44 is an essential molecular marker of cancer stem cells in breast cancer." (PMID 34770956, 2021). "Furthermore, it has been reported that, apart from the standard CD44s isoform, some other CD44 isoforms increase the invasive capability of the MCF7 breast cancer cell line through different pathways, such as CD44st through the Ras/MARK signalling pathway." (PMID 33801148, 2021). "Loss of PRLR expression in HR+ breast cancer cells caused their dedifferentiation generating a mesenchymal-basal-like phenotype enriched in CD44+ breast cancer stem-like cells (BCSCs) showing high tumorigenic and metastatic capacities and resistance to anti-hormonal therapy." (PMID 33446633, 2021). "CD44 is routinely used as a marker of aggressive metastatic breast cancer." (PMID 34579762, 2021). "The results may provide novel insights into the role of CD44-/CD24- tumor cells in delayed breast cancer metastasis and into the potential use of CD44-/CD24- cells as a biomarker to predict survival and metastasis in breast cancer patients." (PMID 34318746, 2021). "Moreover, we discovered that the breast cancer stem-cell marker and metastasis driver CD44, a membrane protein, interacts with MARCH8 and is one of the glycoprotein targets subject to MARCH8-dependent lysosomal degradation." (PMID 34067416, 2021). "To test this hypothesis, we first analyzed some of the most commonly accepted markers for breast cancer stem cells, including CD44 and CD24 expression and ALDH activity." (PMID 34315857, 2021). "In breast cancer, tumor-initiating cancer stem cells express CD44, a transmembrane receptor for hyaluronic acid that is a known effector of metastasis, and maintain low levels of CD24, a sialoglycoprotein that facilitates a number of important signaling networks in development." (PMID 34211050, 2021). "Therefore, CD-44 can be a suitable target for the delivery of anticancer agents specifically to breast cancer cells." (PMID 33530291, 2021). "It has been reported that TM‐induced ER stress could reduce in vitro subpopulation and invasion of CD44+/CD24− phenotype breast cancer stem cells, which indicated the relationship among deglycosylation, ER stress and stemness of cancer cells." (PMID 34320274, 2021). "Xenograft studies of human cell lines show a role for CD44:HA interactions in promoting breast cancer progression while conversely, lung metastasis is enhanced rather than suppressed in a CD44–/– mouse model of mammary gland susceptibility." (PMID 34827550, 2021). "The proportion of CD44+/CD24−/low after chemotherapy therapy was 9.5 times higher than that before chemotherapy in breast cancer, and breast CSCs served as an independent risk factor for predicting poor survival in breast cancer patients." (PMID 34149413, 2021). "In breast cancer, collective cell migration seems to represent the predominant invasion mode, whereby the composition of intercellular contacts varies between invasive ductal carcinoma (adherens junctions) and invasive lobular carcinoma (CD44-mediated)." (PMID 34769389, 2021). "We then analyzed the protein expression of CD44 in various types of human breast cancer cell lines." (PMID 34770956, 2021). "In breast cancer, CD44+CD24− tumor cells were identified as tumorigenic cells." (PMID 33946480, 2021). "In addition, knockdown of CD44 or intratumoral injection of tetrahydrolipostatin (LPL inhibitor) can inhibit breast cancer progression and angiogenesis." (PMID 34834495, 2021).